RPP21 (ribonuclease P subunit p21)
Description:
Component of ribonuclease P, a ribonucleoprotein complex that generates mature tRNA molecules by cleaving their 5'-ends.
Synonyms: C6orf135; CAT60; FLJ22638; Em:AB014085.3
Tractability: PROTAC: ubiquitination databases record sites on it.
Gene: Protein-coding gene on chromosome 6 (30,345,125 to 30,346,884, forward strand). Ensembl gene ENSG00000241370.
Subcellular location: Nucleus, nucleolus
Pathways (Reactome):
Metabolism of RNA: Major pathway of rRNA processing in the nucleolus and cytosol; tRNA processing in the nucleus
Gene Ontology:
Molecular function: protein binding; ribonuclease P activity; ribonuclease P RNA binding
Biological process: response to xenobiotic stimulus; tRNA 5'-leader removal; tRNA processing; RNA processing
Cellular component: multimeric ribonuclease P complex; nucleolar ribonuclease P complex; nucleoplasm; nucleus; endoribonuclease complex; nucleolus; ribonucleoprotein complex
Genetic constraint (gnomAD): Loss-of-function variants: 22 observed, 18.97 expected, observed/expected ratio (o/e) 1.16, 90% interval 0.83 to 1.65. The upper end of that interval is the gene's LOEUF score, 1.65, which puts it in group 6 of 6, group 1 being the genes least tolerant of losing a copy. Missense variants: 215 observed, 198.09 expected, observed/expected ratio (o/e) 1.09, 90% interval 0.97 to 1.22. Synonymous variants: 93 observed, 78.66 expected, observed/expected ratio (o/e) 1.18, 90% interval 1 to 1.4.
Homologues: Orthologues: pig RPP21 (87% identical), guinea pig RPP21 (86% identical), mouse Rpp21 (79% identical), rat Rpp21 (79% identical), tropical clawed frog rpp21 (53% identical), zebrafish rpp21 (52% identical).
Diseases named in the same sentence as RPP21 in open-access papers:
RPP21 is named in the same sentence as 7 diseases in open-access papers, as found by Europe PMC text mining. Sharing a sentence is not in itself a finding about the gene and the disease. The quoted sentences say what the papers report.
hepatoma (1 paper, 2022). "The present results indicated that PHOSPHO2-KLHL23, TSNAX-DISC1, TRIM39 and RPP21 were associated with cell proliferation in SOF-treated hepatoma cells with and without HCV infection." (PMID 35833210, 2022). "Current findings suggested that PHOSPHO2-KLHL23, TSNAX-DISC1, TRIM39 and RPP21 were associated with cell migration in SOF-treated hepatoma cells with and without HCV infection." (PMID 35833210, 2022).
prostate carcinoma (1 paper, 2022). A carcinoma that arises from epithelial cells of the prostate gland. "The DNA damage signature including RPP21 can be employed to define a group of patients of prostate cancer with poor outcome and has the potential to be used as a prognostic marker in treatment." (PMID 35833210, 2022).
tumor (1 paper, 2022). "Second, NGS and TCGA data analysis revealed that several SOF-upregulated genes, including PHOSPHO2-KLHL23, TSNAX-DISC1, TRIM39 and RPP21, were also higher in tumor compared with non-tumor parts in patients with HCC." (PMID 35833210, 2022). "Among these genes, PHOSPHO2, KLHL23, TRIM39, TSNAX-DISC1 and RPP21 expression were significantly elevated in the tumor tissues compared with the non-tumor tissues of HCC according to TCGA database." (PMID 35833210, 2022). "This study found that several genes including PHOSPHO2, KLHL23, TSNAX-DISC1, TRIM39 and RPP21 were upregulated by SOF and the expression levels of these genes were higher in tumor than in non-tumor parts of patients with HCC according to the TCGA database." (PMID 35833210, 2022).
RPP21 also shares sentences with these, for which no sentence is quoted: cancer (2 papers); Behcet disease (1); oral cancer (1); schizophrenia (1).